RNU6-511P (RNA, U6 small nuclear 511, pseudogene)
Gene: Small nuclear RNA gene on chromosome 3 (93,977,029 to 93,977,135, forward strand). Ensembl gene ENSG00000200366.
Homologues: Orthologues: chimpanzee U6 (98% identical), mouse Gm24491 (88% identical), rabbit U6 (84% identical), rabbit U6 (77% identical). Paralogues in human: RNU6-698P (91% identical), RNU6-43P (89% identical), RNU6-1243P (88% identical), RNU6-1331P (88% identical), RNU6-727P (88% identical), RNU6-1060P (87% identical), RNU6-1158P (87% identical), RNU6-11P (87% identical), RNU6-1316P (87% identical), RNU6-1329P (87% identical), RNU6-17P (87% identical), RNU6-18P (87% identical), and 1289 more.